TRAK2 (trafficking kinesin protein 2)
Description:
May regulate endosome-to-lysosome trafficking of membrane cargo, including EGFR.
Synonyms: ALS2CR3; KIAA0549; CALS-C; GRIF-1; OIP98; MILT2; GRIF1
Tractability: Antibody: its Gene Ontology location is reachable by antibodies, with medium confidence. PROTAC: ubiquitination databases record sites on it.
Gene: Protein-coding gene on chromosome 2 (201,377,207 to 201,453,449, reverse strand). Ensembl gene ENSG00000115993.
Subcellular location: Cytoplasm; Early endosome; Mitochondrion
Subcellular location (Human Protein Atlas): Nuclear bodies; Nucleoplasm; Vesicles
Pathways (Reactome):
Signal Transduction: RHOT1 GTPase cycle; RHOT2 GTPase cycle
Gene Ontology:
Molecular function: protein binding; GABA receptor binding; myosin binding; signaling receptor binding; enzyme binding; kinesin binding; TPR domain binding
Biological process: mitochondrion distribution; neurogenesis; protein targeting; vesicle transport along microtubule; dendrite morphogenesis; dendritic transport of mitochondrion; endosome to lysosome transport; negative regulation of axonogenesis; protein O-linked glycosylation; regulation of transcription by RNA polymerase II
Cellular component: cytoplasm; cytoplasmic vesicle; cytosol; dendrite; mitochondrion; plasma membrane; axonal growth cone; dendrite cytoplasm; early endosome; neuronal cell body; nucleus
Genetic constraint (gnomAD): Loss-of-function variants: 67 observed, 91.92 expected, observed/expected ratio (o/e) 0.73, 90% interval 0.6 to 0.89. The upper end of that interval is the gene's LOEUF score, 0.89, which puts it in group 3 of 6, group 1 being the genes least tolerant of losing a copy. Missense variants: 930 observed, 1,047.1 expected, observed/expected ratio (o/e) 0.89, 90% interval 0.84 to 0.94. Synonymous variants: 366 observed, 382.82 expected, observed/expected ratio (o/e) 0.96, 90% interval 0.88 to 1.04.
Homologues: Orthologues: chimpanzee TRAK2 (99% identical), macaque TRAK2 (98% identical), dog TRAK2 (91% identical), pig TRAK2 (91% identical), rabbit TRAK2 (89% identical), mouse Trak2 (88% identical), rat Trak2 (87% identical), guinea pig TRAK2 (85% identical), tropical clawed frog trak2 (60% identical), zebrafish trak2 (52% identical), Drosophila melanogaster milt (27% identical), Caenorhabditis elegans trak-1 (15% identical). Paralogues in human: TRAK1 (46% identical), HAP1 (15% identical).
Diseases named in the same sentence as TRAK2 in open-access papers:
TRAK2 is named in the same sentence as 22 diseases in open-access papers, as found by Europe PMC text mining. Sharing a sentence is not in itself a finding about the gene and the disease. The quoted sentences say what the papers report.
breast carcinoma (3 papers, 2018 to 2023). "In MDA-MB-231 cells, TRAK1 knockdown inhibited, whereas TRAK2 knockdown promoted mitochondrial distribution, showing that their preferential roles in breast cancer cells are anterograde and retrograde trafficking of mitochondria, respectively." (PMID 29992963, 2018). "Protein expression levels of TRAK1 and TRAK2 were significantly high in breast cancer cells with high (H) invasiveness, compared to those with low (L) invasiveness." (PMID 29992963, 2018).
lung carcinoma (2 papers, 2017 to 2019). "High linkage disequilibrium SNPs, which map to a region including CASP8, ALS2CR12 and TRAK2, identified as high-risk SNPs in Chinese esophageal cancer, showed significant associations with the increased risk of lung cancer." (PMID 28542283, 2017). "This is the first study to report that SNPs mapping to TRAK2 were significantly associated with ESCC risk in African populations and support previous findings of an association between rs2244438 and ESCC and lung cancer risk in the Chinese." (PMID 31118947, 2019). "We are the first to report that SNPs mapping to ALS2CR12 and TRAK2 were significantly associated with ESCC and lung cancer of Chinese Han." (PMID 28542283, 2017).
osteosarcoma (2 papers, 2024 to 2025). A usually aggressive malignant bone-forming mesenchymal neoplasm, predominantly affecting adolescents and young adults. "TRAK2 regulates the invasiveness of osteosarcoma by forming a signaling axis with miR-487b, and is a potential therapeutic target and prognostic biomarker." (PMID 40448098, 2025). "Conversely, decreased expression of GLB1L2 and TRAK2 has been documented in prostate cancer and osteosarcoma, respectively." (PMID 38951817, 2024).
schizophrenia (2 papers, 2016 to 2020). A major psychotic disorder characterized by abnormalities in the perception or expression of reality. "Here we demonstrate that the schizophrenia-associated protein, DISC1, interacts with Miro1 and Miro2 as well as TRAK1 and TRAK2 to affect axonal and dendritic transport of mitochondria." (PMID 26553875, 2016). "For example, miR-153 regulates Snap25, Vamp2, Snca, Trak2, Bsn and Pclo genes at the mRNA level; miR-137 inhibits complexin-1, Nsf and Syt1 in mouse model of schizophrenia; miR-34c targets VAMP-2 and miR-135a binds the complexin-1 and complexin-2 genes in the amygdala." (PMID 32252776, 2020).
atopic dermatitis (1 paper, 2018). "Interestingly, the AgNP-associated loci identified Trak2 and Traf6 on chromosomes 1 and 2, previously reported together as genetic variants associated with several common inflammatory diseases including atopic dermatitis, psoriasis, and rheumatoid arthritis." (PMID 29566008, 2018). "Genes of interest are trafficking protein, kinesin binding 2 (Trak2) on chromosome 1 and TNF receptor–associated factor 6 (Traf6) on chromosome 2 because they were discovered together in several previously reported GWAS studies associated with atopic dermatitis, psoriasis, and rheumatoid arthritis." (PMID 29566008, 2018).
bladder cancer (1 paper, 2024). "In conclusion, our analysis confirmed that the ceRNA network YARS1‐hsa‐miR‐148b‐3p/hsa‐miR‐191‐5p‐NFIA/EFEMP1/TRAK2/PAFAH1B1 is associated with bladder cancer prognosis." (PMID 38506098, 2024).
dependence (1 paper, 2018). "Finally, this subnetwork includes three genes that are highly related to GABA synapses (Nsf, Gphn and Trak2); GABA synapses contribute to many of alcohol behaviors, including dependence and withdrawal." (PMID 29674951, 2018).
diabetes (1 paper, 2021). "For example, both ARMC10 and ARMCX3 interact with the Miro/Trak2 complex in mitochondria and thus regulate mitochondrial function to inhibit the progression of AD, PD, diabetes, cancers, mitochondrial diseases, immune-related diseases, and other mitochondrial-related diseases." (PMID 34912852, 2021). "Therefore, ARMCX3 may inhibit the progression of diabetes by interacting with the Kinesin/Miro/Trak2 complex." (PMID 34912852, 2021). "A growing number of studies have shown that mitochondrial dysfunction plays a key role in diabetes, which suggests that ARMC10 inhibits the progression of diabetes by interacting with the KIF5/Miro/Trak2 complex." (PMID 34912852, 2021).
melanoma (1 paper, 2026). A malignant, usually aggressive tumor composed of atypical, neoplastic melanocytes. "In TCGA melanomas, we observed an FDR-significant eQTL for FLACC1 (P = 6.57 × 10−4), as well marginal eQTLs for CASP8 (P = 6.82 × 10−3) and TRAK2 (P = 0.03)." (PMID 41542517, 2026).
thyroid cancer (1 paper, 2025). "A previous study found that metastatic and aggressive thyroid cancer was associated with the loss of TRAK2 expression." (PMID 40448098, 2025).
tobacco use disorder (1 paper, 2026). "The other five loci contained promising coding and expression variants, including Trak2, a gene previously associated with CUD in human GWAS and Slc10a7, Plcl1, and Satb2 which have been associated with alcohol and tobacco use disorder." (PMID 42277005, 2026).
cancer (2 papers, 2019 to 2021). A tumor composed of atypical neoplastic, often pleomorphic cells that invade other tissues. "Therefore, ARMCX3 may inhibit the progression of cancers by interacting with the Kinesin/Miro/Trak2 complex." (PMID 34912852, 2021). "In addition, TRAK1, the ortholog of TRAK2, has been identified as MGb2-Ag—a novel cancer biomarker." (PMID 31242667, 2019).
tumor (2 papers, 2024 to 2025). "The present study identified circSLC22A3 as a new tumor suppressor that inhibited ESCC progression through both the circSLC22A3/ miR-19b-3p/ TRAK2 and circSLC22A3/ IGF2BP1/ ACSBG1 axes." (PMID 40448098, 2025). "Paradoxically, a group of proteins, including C1QL3, EPB41, SNX10, FGF14, GLB1L2 and TRAK2, have been reported as good prognostic markers or tumor suppressors in the NmFMC group." (PMID 38951817, 2024).
cardiovascular disorder (1 paper, 2022). A disease involving the cardiovascular system. "TRAK2 has been reported as a novel regulator of ATP-binding cassette, sub-family A member 1 (ABCA1) expression, cholesterol efflux and HDL biogenesis, and therefore, TRAK2 may be an important target in the treatment of cardiovascular disorders." (PMID 36585686, 2022).
TRAK2 also shares sentences with these, for which no sentence is quoted: esophageal cancer (1 paper); infection (1); mitochondrial disease (1); neuroblastoma (1); prostate carcinoma (1); psoriasis (1); rheumatoid arthritis (1); squamous carcinoma (1).